ALK (ALK receptor tyrosine kinase)
Diseases named in the same sentence as ALK in open-access papers (continued):
Sharing a sentence is not in itself a finding about the gene and the disease.
adenocarcinoma (continued). "All adenocarcinoma patients underwent genetic testing, 75 of who had EGFR mutation, and 3 had ALK mutation." (PMID 36615124, 2022). "Adenocarcinomas harbor targetable genomic alterations in ALK, BRAF, EGFR, and ROS1 genes, and novel treatment options such as KRAS Gly12Cys, MET, NTRK, and RET inhibitors, and possibly ERBB2 guided therapies are broadening the clinical repertoire." (PMID 35964518, 2022). "This case report describes the development of ALK-positive adenocarcinoma in an elderly patient with RA treated with immunosuppressive agents for RA-OP." (PMID 36626420, 2022). "In another case of combined SCLC and adenocarcinoma, an ALK gene alteration was found in both components." (PMID 35677534, 2022). "In total, 140 out of 146 samples (96%) of adenocarcinoma were adequate for ALK, ROS1 and TPS PD‐L1 immunohistochemical assessment, and 137/146 (93.8%) were adequate for molecular profiling." (PMID 35868633, 2022). "Ten patients were female, and all patients had adenocarcinoma histology with advanced ALK-positive NSCLC, which was determined by FISH, immunohistochemistry and/or reverse transcription PCR." (PMID 36612200, 2022). "In young patients, adenocarcinoma is the most frequent histotype and 3–7% expresses the rearrangement of ALK oncogene, sensitive to TKIs." (PMID 35092185, 2022). "In December 2016, a pleuropericardial progression occurred with the need of pericardiocentesis which revealed ALK-positive adenocarcinoma cells." (PMID 35199053, 2022). "There were a higher proportion of adenocarcinoma (85% vs. 71%) and ALK rearrangements (10% vs. 1%) in the group receiving treatment near EOL, but the differences were not significant (both p values = 0.05)." (PMID 35323312, 2022). "The most common histology was adenocarcinoma and activating EGFR mutations or ALK translocations were seen in 31% and 4%, respectively." (PMID 34145985, 2021). "Out of 1967 adenocarcinoma tumors, the EGFR and ALK mutational status was respectively known for 717 (36.4%) and 245 (12.4%) cases." (PMID 34016641, 2021). "By contrast, in 90 patients with ALK-rearranged adenocarcinoma who received crizotinib, strong PD-L1 expression was significantly associated with an unfavorable clinical outcome with shorter progression-free survival and overall survival." (PMID 33806977, 2021). "The clinical characteristics of ROS1- and ALK-rearranged NSCLCs are quite similar: Both rearrangements are more common in younger, never- or light-smoker patients with a histologic diagnosis of adenocarcinoma." (PMID 34884672, 2021). "The aera of personalized treatment, the introduction of targeted therapy was most frequent at adenocarcinoma, especially at young patients (ALK inhibitors), while in older women, the possibility of EGFR inhibition resulted in visible improvement." (PMID 34257563, 2021). "ALK fusions were identified in 343 (5.2%) cases with higher incidences in female, age < 60 or adenocarcinoma patients." (PMID 34271921, 2021). "Some studies have shown that ALK-positive adenocarcinomas were more common in patients at advanced T stages." (PMID 32876329, 2021). "Second, although the current study included a large number of ALK‐positive adenocarcinoma patients, we excluded advanced patients with inoperable tumors." (PMID 34596344, 2021). "In adenocarcinoma, several driver mutations have been identified, including mutations/alterations of the epidermal growth factor receptor (EGFR), anaplastic lymphoma kinase (ALK), and ROS1, among others; most of them are therapeutically targetable." (PMID 33659043, 2021). "Despite their large predominance in adenocarcinomas, ALK rearrangements are also sporadically reported in lung squamous cell carcinoma (SCC)." (PMID 33435440, 2021). "A multivariable logistic regression model was applied to determine the clinical and CT characteristics that can discriminate between ROS1-rearranged and EGFR-mutant or ALK-rearranged adenocarcinomas." (PMID 33005033, 2020).
adenocarcinoma (continued). "87.5% presented with adenocarcinoma histology and 12.5% a mixed histology showing a partial adenocarcinoma differentiation, thus eligible for ALK testing." (PMID 32460789, 2020). "Four patients with adenocarcinoma carried driver mutations (3 had an EGFR tyrosine kinase mutation and 1 had an ALK gene rearrangement)." (PMID 32252414, 2020). "Histopathologically, our CMPT was diagnosed as a benign lesion; however, some reports suggest it to be a precursor of adenocarcinoma because they had confirmed BRAF, EGFR, and ALK mutations, which occur early in lung adenocarcinogenesis." (PMID 32990811, 2020). "Consideration that 16.8% of lung non‐adenocarcinoma individuals with BM were EGFR or ALK positive, we used the adjusted Lung‐molGPA model to assess their survival." (PMID 33027555, 2020). "Most patients (n=32; 94.1%) had adenocarcinoma; 12 (35.3%) patients had confirmed EGFR mutation, while two (5.9%) had ALK translocation." (PMID 33033525, 2020). "Out of the 29 adenocarcinoma patients, 10 had active driver mutations, distributed into EGFR mutation (n = 9), and ALK rearrangement (n = 1)." (PMID 32767461, 2020). "ALK rearrangement was more frequent in adenocarcinomas with a mucus‐producing component, micropapillary structure and visceral pleura invasion." (PMID 32729257, 2020). "Histologic transformation of NSCLC to SCLC has already been recognized as a crucial mechanism of acquired resistance to EGFR- or ALK-TKI in EGFR-mutated or ALK+ adenocarcinomas." (PMID 32299384, 2020). "In patients with advanced NSCLC, EGFR mutations, ALK gene fusion, RET gene fusion, younger age (≤60 years), lymph node N2‐N3 metastasis and the pathological type of adenocarcinoma are all independent risk factors for brain metastasis." (PMID 31769228, 2020). "Our study showed that in a cohort of patients with advanced adenocarcinomas, patients with ROS1-rearranged tumors exhibit characteristic clinical and radiologic features compared to those with EGFR mutations or ALK rearrangement." (PMID 33005033, 2020). "In contrast, ALK mutations were more common in NSCC, favor adenocarcinoma (4.2% vs 8.4%, P = 0.021)." (PMID 32429938, 2020). "ALK rearrangement was more frequent in adenocarcinomas with mucus‐producing component (P < 0.001), micropapillary structure (P = 0.004) and invasion of the visceral pleura of the lung (P = 0.048)." (PMID 32729257, 2020). "Patients with stage IIIb/IV adenocarcinoma with ROS1 rearrangement, EGFR mutations, or ALK rearrangement were retrospectively identified." (PMID 33005033, 2020). "After biopsy, the abdominal lymph nodes were identified as adenocarcinoma originating from the lung following computed tomography (CT) scan, and ALK rearrangement was confirmed." (PMID 31588629, 2019). "His adenocarcinoma was positive for ALK according to immunohistochemistry and fluorescence in situ hybridization (FISH) method." (PMID 31030664, 2019). "In this study, the overall positive rate of ALK fusion was 16%, and up to 59% of adenocarcinomas with poor differentiation exhibited an ALK fusion, consistent with previous reports." (PMID 31387567, 2019). "This is significant because ALK rearranged adenocarcinomas are resistant to the commonly used EGFR kinase inhibitors." (PMID 30546837, 2018). "The tyrosine kinase receptors involved in the translocations of adenocarcinoma include anaplastic lymphoma kinase (ALK) (2p23), ROS1 (6q22), and RET (10q11)." (PMID 30336782, 2018). "A 65-year-old female with clinical stage IIIA-N2 ALK-rearranged adenocarcinoma originating from the left lower lobe presented." (PMID 29524063, 2018). "In FISH reaction, we confirmed the presence of ALK gene rearrangement only in samples with expression of abnormal ALK protein visualized in IHC assay and only in adenocarcinomas." (PMID 28534101, 2017). "The rate of ALK gene fusions in our study (11.5%) was slightly higher than those reported previously for Chinese patients with adenocarcinomas (5.1–10%)." (PMID 28673332, 2017).
adenocarcinoma (continued). "For the non-adenocarcinoma cases that were ALK positive by IHC in the triple-negative cohort, NanoString analysis suggested overexpression of the entire gene by some other mechanism than gene rearrangement (see, e.g.)." (PMID 28415793, 2017). "ROS1- and RET-rearranged adenocarcinomas have a similar histology to ALK-rearranged adenocarcinoma, such as mucinous cribriform pattern or solid signet-ring cell pattern." (PMID 28894699, 2017). "ALK-rearranged adenocarcinoma is characterized by a TTF-1 cell lineage, an acinar structure with mucin/signet-ring cell pattern, non-/light-smoking history, and young onset." (PMID 28894699, 2017). "Mutations in epidermal growth factor receptor (EGFR) or rearrangements in the anaplastic lymphoma kinase (ALK) gene are the most common findings—almost 25% of adenocarcinoma cases." (PMID 28430151, 2017). "Among HER2-amplified adenocarcinomas, 24 (52.2%) and 3 (6.5%) had EGFR and KRAS mutations, respectively, while 1 (2.2%) showed ALK rearrangement." (PMID 28146588, 2017). "All sample histologies were adenocarcinomas with the exception of two cases of adenosquamous tumors from the ALK RT-PCR-positive group." (PMID 28763012, 2017). "In two patients with adenocarcinoma of the lung driver mutations were detected (EGFR Exon 19 deletion and ALK rearrangement) out of the lymph node metastasis." (PMID 28693444, 2017). "All 33 patients were diagnosed pathologically as having adenocarcinoma; 10 (30.3%) tested by Ventana ALK(D5F3)-positive and 23 (69.7%) tested by FISH-positive." (PMID 28427213, 2017). "ALK rearrangement is more frequent in acinus forms of adenocarcinomas of Asian patients and in signet-ring cell adenocarcinomas of Caucasian patients." (PMID 28805682, 2017). "For adenocarcinoma, the dominant histological subtype of lung cancer, increased understanding of molecular pathogenesis such as EGFR mutation, KRAS mutation and ALK fusion leads to the success of targeted therapy." (PMID 28852126, 2017). "ALK-rearranged NSCLC are typically adenocarcinoma characterized by a solid signet-ring cell pattern that is frequently associated with a metastatic phenotype." (PMID 27119231, 2016). "Echinoderm microtubule-associated protein-like 4 (EML4)-ALK fusion proteins were recently detected in 3–5 % of NSCLC, particularly in adenocarcinomas." (PMID 26970967, 2016). "ALK-rearranged NSCLC is typically an adenocarcinoma that exhibits unique histological features represented by solid tumor growth and frequent signet-ring cells with abundant intracellular mucin." (PMID 27119231, 2016). "With the development of targeted therapy, adenocarcinoma are classified into subsets, such as epidermal growth factor receptor (EGFR)-mutated type, anaplastic lymphoma kinase (ALK)-rearranged type and ROS1-rearranged type." (PMID 27708233, 2016). "Our case is the first report of crizotinib effective for ALK-positive adenocarcinoma with adnexal metastasis." (PMID 27472693, 2016). "Of the adenocarcinomas, 2,295 (46%) tumors had EGFR mutations, 358 (9.2%) had KRAS mutations, and 270 (7.2%) had ALK rearrangements." (PMID 26992209, 2016). "Crizotinib therapy provided treatment benefit in ALK-rearranged adenocarcinoma patients especially in advanced stages of the disease." (PMID 27142166, 2016). "The diagnosis was adenocarcinoma, and moreover molecular analysis revealed that ALK protein was positive by immunohistochemical staining and ALK rearrangement was positive by reverse transcription polymerase chain reaction (RT-PCR)." (PMID 26987388, 2016). "Between March 2000 and February 2015, ALK-rearrangement was confirmed in 76 patients at our institution; all had adenocarcinomas." (PMID 27756333, 2016). "Patients with advanced adenocarcinomas are currently tested for EGFR mutations, ALK aberrations, and ROS1 in routine clinical practice." (PMID 26970967, 2016). "Crizotinib therapy possesses clinical benefits for ALK-rearranged adenocarcinoma patients, comparable with previous studies." (PMID 27142166, 2016).
adenocarcinoma (continued). "Previous reports mostly demonstrated ALK rearrangement frequencies of 3-5 % in unselected patient populations, 3–25 % in adenocarcinomas, and 33 % in highly selected patient populations (EGFR wild-type, female, non/light smokers)." (PMID 27495736, 2016). "In this study, the prevalence of ALK-rearranged adenocarcinoma patients was similar to previous published data and was significantly associated with younger patients, females and non-smoking status." (PMID 27142166, 2016). "EML4-ALK NSCLC patients (adenocarcinoma only) treated with ALK-inhibitor have also been shown to achieve long-term median survival." (PMID 27542716, 2016). "In terms of disease outcomes, ALK-rearranged adenocarcinoma patients who were in the early stages and had resectable disease showed excellent prognosis even without crizotinib therapy." (PMID 27142166, 2016). "Ten of 14 adenocarcinomas underwent molecular mutational profiling: 2/8 had KRAS mutation, 1/10 had EGFR mutation, and 0/5 had ALK rearrangement." (PMID 25689302, 2015). "Intriguingly, we found 4 ALK-rearranged adenocarcinomas with morphologic features of focal squamous differentiation." (PMID 26253541, 2015). "More specifically ALK rearrangement was found in 4 adenocarcinomas (1 female, 3 male patients) all with advanced stage disease." (PMID 26208325, 2015). "Another important mutation, the anaplastic lymphoma kinase (ALK) translocation, is responsible for approximately 3–5 % of non-small-cell lung cancer (NSCLC) and is found predominately in adenocarcinomas." (PMID 26582178, 2015). "Of 32 patients with adenocarcinoma, 14 were found to be positive for the EGFR mutation, 14 were negative for the EGFR mutation and 4 patients were positive for anaplastic lymphoma kinase (ALK) fusion." (PMID 25490772, 2014). "It defines a distinct molecular subset of NSCLC, in particular adenocarcinoma that can benefit by the treatment of ALK-inhibitors." (PMID 25527865, 2014). "ALK fusion has also been found in older patients, smokers, patients with EGFR mutation and non-adenocarcinoma histological subtypes, such as adenosquamous carcinoma and large cell carcinoma." (PMID 24404167, 2014). "The frequency of ALK rearrangement in nGGO was significantly lower than previously reported in adenocarcinoma." (PMID 24885886, 2014). "Here we report a case of a patient with NSCLC adenocarcinoma, with ALK-rearrangement and bone, lymph nodal and choroidal metastases at diagnosis, who showed an impressive response to crizotinib in all sites." (PMID 25178493, 2014). "Several studies have revealed that adenocarcinomas with ALK rearrangement have more lymph node metastases." (PMID 24885886, 2014). "Last but not the least, there were many other clinicopathological or demographical characteristics that were poorly known, such as high frequencies of signet-ring cell and mucinous cribriform patterns in ALK rearranged adenocarcinomas." (PMID 24959902, 2014). "While acinar and lepidic predominant adenocarcinoma were significantly lower in ALK positive patients (P < 0.05)." (PMID 24667260, 2014). "Currently, we can offer these treatments routinely to patients with EGFR-mutated and ALK-rearranged NSCLC, the vast majority of whom have adenocarcinoma histology." (PMID 25157335, 2014). "It is of interest to note that Asian NSCLC patients who had ALK rearrangements shared similar features to those with EGFR mutations in terms of gender, smoking status and adenocarcinoma." (PMID 24959902, 2014). "Thyroid transcription factor-1 (TTF-1) is a marker of TRU-type adenocarcinoma, and two studies concerning 11 and 12 ALK-positive patients each revealed TTF-1 positivity in all ALK-positive adenocarcinomas." (PMID 24885886, 2014). "The proportion of solid predominant adenocarcinoma was significantly higher in ALK positive patients (P < 0.05)." (PMID 24667260, 2014).
adenocarcinoma (continued). "Pathological characteristics of the ALK-positive tumors were as follows: 43 (91.5%) adenocarcinomas (ACs), one (2.1%) SCC, and three (6.4%) NSCLCs NOS." (PMID 25248157, 2014). "Six ALK rearrangement-positive (ALK-positive) nGGOs were invasive adenocarcinomas, whereas 11.8% (14 out of 119) of EGFR mutation-positive nGGOs were pre-invasive or minimally invasive adenocarcinomas." (PMID 24885886, 2014). "Adenocarcinoma with ALK rearrangement is usually found in younger, female patients who have light to no smoking history, and has been reported to have acinar, papillary, cribriform, and signet-ring patterns." (PMID 24885886, 2014). "In the present study, cases harboring ALK rearrangement were selected on the basis of previously documented characteristic features, including adenocarcinoma histology and mucin production." (PMID 25295103, 2014). "In EGFR and KRAS-wild type adenocarcinomas (EGFRwt/KRASwt), different potential drivers of pathogenesis exist, including ALK, RET, and ROS1 gene fusions, with ALK rearrangements being therapeutically relevant." (PMID 24205279, 2013). "ALK rearrangement was identified in 2 samples (1.0%) from the test set and both cases were adenocarcinoma (2/148 adenocarcinomas; 1.4%)." (PMID 23936355, 2013). "Fusion and split FISH analyses using probes for EML4 and ALK genes confirmed that the adenocarcinoma of the right lung was indeed EML4-ALK positive." (PMID 23617234, 2013). "ALK rearrangements were found only in adenocarcinoma histology; however, various predominant histological subtypes were observed among them." (PMID 23936355, 2013). "Four of the 5 ALK positive adenocarcinoma patients showed a solid and acinar growth pattern and, in addition, four of the five showed a pattern with signed ring cells was present." (PMID 23359795, 2013). "As previously reported, ALK positive patients were predominantly adenocarcinomas, with low previous smoking history and tend to be younger than the amount of NSCLC patients." (PMID 23359795, 2013). "The majority of NSCLCs that are ALK positive exhibit adenocarcinoma histology, and are likely to occur in individuals with little or no tobacco exposure." (PMID 22374459, 2012). "KRAS positive mutations are limited to NSCLC (predominantly adenocarcinomas) and are mutually exclusive to mutations in EGFR and ALK." (PMID 23109866, 2012). "Current estimates suggest that the EML4-ALK fusion is present in approximately 3–6 % of adenocarcinomas, depending upon on the population studied and the ALK detection methods used." (PMID 22825000, 2012). "Patients with ALK fusion adenocarcinomas confirmed by FISH have been shown to respond favourably to crizotinib treatment, and a phase III trial is currently ongoing." (PMID 22825000, 2012). "In this study, the frequency of ALK gene rearrangements detected using a dual-color break-apart FISH probe was 3.7% of adenocarcinoma cases." (PMID 23198868, 2012). "ALK-driven tumors are almost exclusively adenocarcinomas and are targetable with ALK inhibitors." (PMID 41594221, 2026). "Continuing lorlatinib may contribute to intracranial disease management and provided sustained disease control of the ALK-rearranged adenocarcinoma." (PMID 41584719, 2026). "As for EGFR mutations, ALK fusions are more common for never smokers and patients with adenocarcinoma histology." (PMID 40136350, 2025). "Non-small cell lung cancer (NSCLC) and EGFR/ALK inhibitors affect patients with NSCLC (those with adenocarcinoma and who are not smokers) who have mutations in the EGFR genes or rearrangements in the ALK gene." (PMID 40647400, 2025). "There are well-known facts on the association of NSCLC genotypes with such factors, e.g., EGFR mutations and ALK fusions prevail in female patients with adenocarcinoma of younger age and no history of smoking, while KRAS mutations are more common in smokers." (PMID 40809430, 2025).